FADS2 (fatty acid desaturase 2)
Diseases named in the same sentence as FADS2 in open-access papers (continued):
Sharing a sentence is not in itself a finding about the gene and the disease.
steatosis (10 papers, 2017 to 2025). Increased lipid within the cytoplasm of cells. "The aggravated steatosis under loss of FADS2 is therefore solely associated with increased abundancy in TAG species containing fatty acid chains with lower degrees of unsaturation." (PMID 36823355, 2023). "While FADS2 loss aggravated steatosis phenotypes, its overexpression resulted in steatosis reduction." (PMID 36823355, 2023). "While FADS2 deficiency exacerbated the steatosis phenotype, overexpression of FADS2 resulted in reduced steatosis." (PMID 37175830, 2023). "We first analyzed total TAG content within these different FADS2 variant organoids, which photocopied the observed steatosis trend." (PMID 36823355, 2023). "Our functional data position FADS2 as an important steatosis mediator and putative target, and furthermore suggest that genetic variation in FADS2 may confer susceptibility to steatosis." (PMID 36823355, 2023). "To further evaluate the role of FADS2, we questioned whether FADS2 KO would predispose WT human hepatocytes to steatosis." (PMID 36823355, 2023). "After interrogating 35 candidate genes, they found the perturbation of FADS2, an enzyme mediating the rate-limiting step in the biosynthesis of polyunsaturated fatty acids (PUFAs), aggravated steatosis in FatTracer." (PMID 37009924, 2023). "During CRISPR-LOF screening on FatTracer platform and subsequent functional characterization, they identified FADS2 as a critical mediator for steatosis." (PMID 37009924, 2023). "We therefore generated FADS2−/− organoid lines, which indeed spontaneously accumulated lipids in basal culture conditions (roughly 5% steatosis)." (PMID 36823355, 2023). "When challenged with a mild dose of FFAs (320 μM), FADS2−/− organoids displayed a markedly aggravated steatosis phenotype compared with FADS2WT organoids challenged with the same FFA dose, further strengthening the evidence of an important role for FADS2 in balancing lipid homeostasis." (PMID 36823355, 2023). "We next generated FADS2OE lines in WT organoids to evaluate whether FADS2 overexpression could confer protection against FFA-induced steatosis." (PMID 36823355, 2023). "Further validation by knockout FADS2 in WT organoids also phenocopied steatosis." (PMID 37009924, 2023). "This platform, termed FatTracer, identified FADS2 as a critical steatosis modulator." (PMID 36823355, 2023). "Of note, only a mild threshold level of FADS2 overexpression was needed to reduce steatosis." (PMID 36823355, 2023). "Initially identified from our CRISPR-LOF screening by exacerbated steatosis, we found that increasing FADS2 protein could effectively prevent and resolve steatosis." (PMID 36823355, 2023). "Therefore, modulation of the level of FADS2 expression directly determines the level of steatosis within hepatocytes, both in developing and pre-existing steatosis." (PMID 36823355, 2023). "Interestingly, overexpression FADS2 alleviated steatosis in both FatTracer and FFA induced models." (PMID 37009924, 2023). "Thus, a FADS2-regulated PUFA–DNL axis may represent a functional mechanism to influence steatosis levels within the hepatocyte." (PMID 36823355, 2023). "From this CRISPR screen, FADS2 (but not FADS1) emerged as a critical player in steatosis." (PMID 36823355, 2023). "We next used these lines to elucidate the interplay between the lack of FADS2 and a FFA-induced steatosis trigger." (PMID 36823355, 2023).
glioblastoma (9 papers, 2020 to 2025). The most malignant astrocytic tumor (WHO grade IV). "FADS2 is upregulated in glioblastoma, and its deficiency inhibited glioblastoma cell proliferation, which offers a potential novel therapeutic target." (PMID 34819946, 2021). "Furthermore, FADS2 activity leads to greater glioblastoma tumor growth and radioresistance, which is associated with the production of ARA C20:4n-6." (PMID 37046844, 2023). "Three studies focused on PUFA status and genetic variation in FADS1/FADS2 genes, two on prostate cancer and one on glioblastoma multiforme." (PMID 40430008, 2025). "A previous study demonstrated that glioblastoma tumors downregulate FADS2 expression, potentially mitigating oxidative stress or reallocating metabolic resources." (PMID 40430008, 2025). "Expression data for ELOVL1, ELOVL3, ELOVL6, SCD, and FADS2 were obtained from raw data published in our previous papers, where we examined the expression of elongases and desaturases in glioblastomas." (PMID 37239243, 2023). "Subsequently, we show that recurrent patient-derived glioblastoma cells can be re-sensitized to TMZ either by supplementing the fatty acid palmitate to media or by targeting SCD or FADS2." (PMID 36338708, 2022). "Therefore, FADS2/D6D inhibitors such as SC-26196 exhibit in vivo antitumor activity against glioblastoma." (PMID 37046844, 2023). "Similar to FADS1, FADS2 expression may depend on the type of glioblastoma cell." (PMID 37046844, 2023). "Another case–control study examined the expression of desaturases (FADS1, FADS2, and SCD) in glioblastoma tumors from 28 patients." (PMID 40430008, 2025). "Targeting key lipid metabolism enzymes (SCD, FADS2, ACLY, and ACSL) to re-sensitize cancer cells to chemotherapy has already been demonstrated as a successful approach to combat glioma and glioblastoma." (PMID 38609948, 2024). "We also examined the effect of GZ17-6.02 on recently identified glioblastoma super-enhancer genes WSCD1, EVOL2, and KLHDC8A as well as the enzyme FADS2, which mediates ELOVL2 signaling." (PMID 35456993, 2022). "Using single cell sequencing data of glioblastoma tissue from patients, we observed that the expression of FASN, SCD and FADS2 correlated with distinct cell fates within the cancer cell cluster." (PMID 36338708, 2022). "In glioblastoma cancer stem cells, FADS2 expression is higher than in nonstem cancer cells, and its activity is critical for cell viability and self-renewal." (PMID 37046844, 2023). "The expression of FADS2 is elevated in glioblastoma tumors compared to nontumor brain tissue." (PMID 37046844, 2023). "Thus, we performed GC-MS based analysis of the total fatty acid in eight human glioblastoma tumors and found that, overall, GBM tumors have nearly equivalent relative SCD activity (palmitoleate to palmitate ratio) and FADS2 activity (sapienate to palmitate ratio)." (PMID 36338708, 2022).
Crohn disease (8 papers, 2016 to 2025). A gastrointestinal disorder characterized by chronic inflammation involving all layers of the intestinal wall, noncaseating granulomas affecting the intestinal wall and regional lymph nodes, and transmural fibrosis. "rs102275, an intronic variant in TMEM258 associated with Crohn’s disease, is an eQTL for FADS2 in all cell types examined." (PMID 27015630, 2016). "Taken together, our data suggest that FADS2 could have a pathogenic role, as TNFα is the most common treatment target in Crohn’s disease." (PMID 34229738, 2021). "Furthermore, by integrating our data with other public data, we confirmed the association between FADS2 and Crohn’s disease and the association between arachidonic acid and Crohn’s disease." (PMID 34229738, 2021). "Equivalently, but except for SNP rs17831757, the high ratio of n-6 to n-3 PUFAs increased the odds ratio of Crohn's disease in the subjects who have the alleles of 3 SNPs in FADS2, which are associated with high plasma levels of n-3 PUFAs and low plasma levels of n-6 PUFA." (PMID 30402511, 2018). "However, the risk allele (G) for Crohn’s disease is associated with increased, not decreased, FADS2 expression, suggesting that higher FADS2 expression may in fact increase IBD susceptibility." (PMID 27015630, 2016).
bladder cancer (7 papers, 2021 to 2025). "In conclusion, this study highlights FADS2 as a key player in ferroptosis escape in bladder cancer and unveils a novel mechanism underlying this resistance." (PMID 40682485, 2025). "In previous studies, FADS2 was identified as a gene associated with ferroptosis in bladder cancer." (PMID 40682485, 2025). "Building on previous findings, FADS2 is implicated in ferroptosis resistance in bladder cancer." (PMID 40682485, 2025). "Further investigation is warranted to elucidate how AhR signaling regulates the expression or activity of FADS1 and FADS2 in bladder cancer, which may help uncover the mechanisms underlying the altered MUFA/PUFA ratio observed in our study." (PMID 40557796, 2025). "The mechanisms underlying the regulatory role of FADS2 in cancer cells may provide a novel perspective for the future treatment of bladder cancer." (PMID 35145965, 2022). "Clinical correlation analysis revealed that FADS2 expression increased with the advancement of bladder cancer stage, reinforcing its potential as a prognostic marker." (PMID 40682485, 2025). "In this study, bioinformatics analyses and immunohistochemical staining revealed that FADS2 is aberrantly overexpressed in bladder cancer, with its high expression correlating with poor prognosis." (PMID 40682485, 2025). "FADS2 regulates ferroptosis in bladder cancer by influencing the expression of GPX4 and SLC7A11, but the upstream regulators of FADS2 remain to be explored." (PMID 40682485, 2025). "FADS2 knockdown led to a significant increase in both GSH depletion and MDA accumulation compared to the control group, confirming a marked increase in lipid ROS levels following FADS2 inhibition in bladder cancer cells." (PMID 40682485, 2025). "In vitro, CCK‐8 and colony formation assays showed that silencing FADS2 inhibited bladder tumour growth, while migration and scratch assays demonstrated that FADS2 knockdown reduced the migration capacity of bladder cancer cells." (PMID 40682485, 2025). "Ki67 immunohistochemical staining further confirmed that FADS2 knockdown inhibited bladder cancer growth in vivo." (PMID 40682485, 2025). "Collectively, these findings suggest that FADS2 plays a role in ferroptosis resistance in bladder cancer and that FADS2 knockdown enhances the sensitivity of bladder cancer cells to ferroptosis." (PMID 40682485, 2025). "Collectively, these findings support the potential of FADS2 as a valuable prognostic biomarker in bladder cancer." (PMID 40682485, 2025). "Analysis of the TCGA database revealed a significant positive correlation between FADS2 expression in bladder cancer and the activity markers SCD and FASN, which reflect SREBP activity." (PMID 40682485, 2025). "Bioinformatics analysis of bladder cancer transcriptome data from the TCGA database revealed a significant positive correlation between FADS2 expression and SCD and FASN, molecules that reflect SREBP activity." (PMID 40682485, 2025). "Colony formation assays further showed that the FADS2 knockdown group formed fewer and smaller colonies, collectively indicating that decreased FADS2 expression suppresses bladder cancer cell proliferation." (PMID 40682485, 2025). "Paired differential analysis showed that FADS2 was significantly overexpressed in bladder cancer compared to normal bladder tissue." (PMID 40682485, 2025). "Both in vivo and in vitro experiments, including CCK‐8 assays, lipid peroxidation assays, iron measurements and ferroptosis‐related gene analyses, demonstrated that silencing FADS2 can trigger ferroptosis in bladder cancer cells." (PMID 40682485, 2025). "Overall, these in vivo findings support the in vitro data, demonstrating that FADS2 knockdown inhibits bladder cancer growth by promoting ferroptosis." (PMID 40682485, 2025). "Building on the observation of FADS2's differential expression, its prognostic relevance in bladder cancer was further evaluated." (PMID 40682485, 2025).
bladder cancer (continued). "In previous bioinformatics analyses, FADS2 was identified as a ferroptosis‐related gene in bladder cancer." (PMID 40682485, 2025). "Mechanistically, inhibition of the mTOR pathway and SREBP activity was found to reduce FADS2 expression and promote ferroptosis in bladder cancer." (PMID 40682485, 2025). "In this study, we confirmed that FADS2 expression was significantly improved in bladder cancer cells." (PMID 35145965, 2022). "Detailed studies regarding the mechanism of action of FADS2 in bladder cancer are ongoing at our centre, which will provide a novel perspective for the future treatment of bladder cancer." (PMID 35145965, 2022). "The results indicated that FADS2 protein was overexpressed in most of these bladder cancer cells except for RT-112, whereas HMGCR was overexpressed in T24, RT-112 and 5,637 cells." (PMID 35145965, 2022). "The mRNA and protein levels of FADS2, a typical ferroptosis-related gene used in the study, were higher in bladder cancer cell lines than in controlled SV-HUC-1 cells." (PMID 35145965, 2022). "Consequently, FADS2 knockdown plasmids were transfected into 5637 and BIU‐87 cells to establish bladder cancer cells with reduced FADS2 expression, and the transfection efficiency was confirmed." (PMID 40682485, 2025). "In conclusion, these findings underscore the critical role of FADS2 in ferroptosis resistance and suggest that its inhibition could increase the sensitivity of bladder cancer cells to ferroptosis." (PMID 40682485, 2025). "Additionally, FADS2 knockdown enhanced the sensitivity of bladder cancer cells to FINs, suggesting that elevated FADS2 expression contributes to ferroptosis resistance in bladder cancer." (PMID 40682485, 2025). "In conclusion, this study identifies a critical gene involved in ferroptosis escape in bladder cancer and suggests that FADS2 could serve as a novel prognostic marker and therapeutic target." (PMID 40682485, 2025). "This study, therefore, aims to investigate whether FADS2 contributes to ferroptosis resistance in bladder cancer and whether it could serve as a novel therapeutic target and prognostic biomarker." (PMID 40682485, 2025). "Our future research will focus on whether inhibiting FADS2 expression can enhance the efficacy of chemotherapy and immunotherapy in bladder cancer." (PMID 40682485, 2025). "Notably, our analysis showed that patients with bladder cancer exhibiting high FADS2 expression were more sensitive to the mTOR inhibitor rapamycin." (PMID 40682485, 2025). "Furthermore, Ki67 immunohistochemical staining revealed a positive correlation between FADS2 expression and tumour malignancy, further supporting the prognostic significance of FADS2 in bladder cancer." (PMID 40682485, 2025). "Furthermore, immunohistochemical staining analysis from the HPA database also showed a marked increase in FADS2 expression in bladder cancer tissues." (PMID 40682485, 2025). "Additionally, univariate and multivariate Cox regression analyses demonstrated that FADS2 expression serves as an independent predictor of adverse prognosis in patients with bladder cancer." (PMID 40682485, 2025). "Although prognostic prediction models based on ferroptosis‐related genes in bladder cancer have been developed, the specific role of FADS2 in this context remains unclear." (PMID 40682485, 2025). "Both in vitro and in vivo, FADS2 knockdown inhibited the proliferation of bladder cancer cells." (PMID 40682485, 2025). "Moreover, Cox regression analysis suggested that FADS2 could serve as an independent prognostic factor for bladder cancer." (PMID 40682485, 2025). "Thus, it is hypothesised that mTOR activation upregulates SREBP activity, which in turn promotes FADS2 overexpression, contributing to ferroptosis resistance in bladder cancer cells and facilitating cancer progression." (PMID 40682485, 2025).
bladder cancer (continued). "Initial analysis revealed low FADS2 expression in SV‐HUC‐1, a normal human ureteral epithelial cell line, and high expression in bladder cancer cell lines, particularly 5637 and BIU‐87." (PMID 40682485, 2025). "This study and our previous research have both indicated vital regulatory roles of FADS2 and HMGCR in bladder cancer development, thus these two ferroptosis-related genes were further verified by experiments in this study." (PMID 35145965, 2022). "The in vitro detection revealed that both mRNA and protein levels of FADS2 and HMGCR were generally increased in bladder cancer cells as compared with normal cells, which was consistent with our analyses from public TCGA and GEO datasets." (PMID 35145965, 2022). "This led to the hypothesis that activation of the mTOR pathway promotes FADS2 overexpression by enhancing SREBP activity, thereby contributing to the resistance of bladder cancer cells to ferroptosis." (PMID 40682485, 2025). "In bladder cancer, paired differential analysis revealed significantly higher FADS2 expression in tumour tissues compared to adjacent noncancerous tissues." (PMID 40682485, 2025). "However, the detailed expression patterns of FADS2 in bladder cancer cells have never been investigated through experimental validation." (PMID 35145965, 2022). "Thus, we infer that FADS2, FANCD2 and HMGCR play a negative role in ferroptosis during bladder cancer development." (PMID 34095228, 2021).
asthma (6 papers, 2020 to 2025). "FADS2 has been linked to adult asthma in European backgrounds, and key inflammatory metabolites have been identified near FADS2." (PMID 35448546, 2022). "FADS1 and FADS2 were linked to asthma in several previous studies." (PMID 40676019, 2025). "Interestingly, among the overlap with cis-mQTLs, the top gene based on significance was FADS2; its associated polymorphisms modulate fatty acid metabolism and influence asthma risk." (PMID 33468710, 2021). "Moreover, decreased activity of FADS2 is accompanied by asthma progression, which might be caused by the interrupted metabolism of polyunsaturated fatty acids (PUFAs) and pro-resolving lipid mediator synthesis." (PMID 35448546, 2022). "Notably, decreased activity of FADS1 and FADS2 (fatty acid desaturase 1 and 2) are markers of asthma progression." (PMID 37680636, 2023). "Mutations in Fatty Acid Desaturase 2 (FADS2) affected the levels of 1-arachidonoyl-GPA (20:4), and Mendelian Randomization analyses revealed that high genetically regulated 1-arachidonoyl-GPA (20:4) levels were associated with increased odds of asthma (p < 0.001)." (PMID 35448546, 2022). "This is consistent with an observational study that showed that high levels of 1-arachidonoyl-GPA (20:4) were correlated with asthma, and 1-arachidonoyl-GPA (20:4) is influenced by FADS2." (PMID 35448546, 2022).
atherosclerosis (6 papers, 2015 to 2021). A disease characterized by the build-up of fatty material and calcium deposition in the arterial wall resulting in partial or complete occlusion of the arterial lumen. "Cellular enrichment of ≥20 PUFAs beyond the rate-limiting FADS2 enzyme are equally effective in preventing atherosclerosis and hepatosteatosis." (PMID 28750643, 2017).